PLXNA1 (plexin A1)
Diseases named in the same sentence as PLXNA1 in open-access papers (continued):
Sharing a sentence is not in itself a finding about the gene and the disease.
Kallmann syndrome (1 paper, 2023). Kallmann syndrome (KS) is a developmental genetic disorder characterized by the association of congenital hypogonadotropic hypogonadism (CHH) due to gonadotropin-releasing hormone (GnRH) deficiency, and anosmia or hyposmia (with hypoplasia or aplasia of the olfactory bulbs). "Heteroinsufficiency of SEMA3A or its receptor PLXNA1 is implicated in Kallmann syndrome, a genetic disorder with neurological defects in odor detection." (PMID 37941606, 2023).
malignant mesothelioma (1 paper, 2013). A malignant neoplasm of the pleura or peritoneum, arising from mesothelial cells. "Plexin-A1, the gene identified in our study, has been shown to activate the VEGF receptor and NF-κB to promote survival of malignant mesothelioma cells, suggesting a complex interplay of PLXNA1 in cell survival and neovascularization." (PMID 24009521, 2013).
multiple sclerosis (1 paper, 2019). A progressive autoimmune disorder affecting the central nervous system resulting in demyelination. "In order to evaluate the Plexin‐A1 level of expression in the context of multiple sclerosis, we first performed data mining from published gene array profiles using the GEO platform." (PMID 31566924, 2019). "Altogether, our results suggest a therapeutic potential of inhibiting Plexin‐A1 in myelin diseases such as multiple sclerosis in which we found overexpression of Plexin‐A1." (PMID 31566924, 2019).
osteoporosis (1 paper, 2022). A condition of reduced bone mass, with decreased cortical thickness and a decrease in the number and size of the trabeculae of cancellous bone (but normal chemical composition), resulting in increased fracture incidence. "This study aimed to explore the associations of genetic variants in the semaphorin 3A (SEMA3A) signaling pathway genes, including SEMA3A, NRP1, PLXNA1, PLXNA2 and PLXNA3 with osteoporosis (OP) risk and bone mineral density (BMD) in a Chinese Han older adult population." (PMID 36425469, 2022).
prostate tumors (1 paper, 2022). "The increased expression of PLXNA1 promoted the growth of prostate tumors and independently predicted the biochemical recurrence, metastasis, and poor survival of prostate tumors in a multi-institutional PCA patient cohort." (PMID 36035171, 2022).
renal cell carcinoma (1 paper, 2025). "For example, both NRP2 and PLXNA1 are significantly upregulated in renal cell carcinoma (the Human Protein Atlas), which may be a promising target cancer type for therapeutic investigations of P1943-Nb2cL." (PMID 41391772, 2025).
renal clear cell carcinoma (1 paper, 2022). "Furthermore, PLXNA1 is also a promising therapeutic target for renal clear cell carcinoma." (PMID 36035171, 2022).
tumor (31 papers, 2013 to 2026). "Once tumor-associated macrophages are in the hypoxic areas of the tumor, they remain there because of plexinA4/plexin-A1 signals." (PMID 37627074, 2023). "Plexin-A4 (or plexin-A1) in a complex with NRP-1 can transduce sema3A attractive signals involving VEGFR1 for tumor-associated macrophages after hypoxia induction." (PMID 37627074, 2023). "We next identified a developmental and tumor-associated pro-angiogenic role of Plexin-A1." (PMID 27506939, 2016). "In the female-specific panel, genes related to aberrant androgen signaling across tumor types like androgen receptor, PLXNA1, USP54, and PMEPA1 were influential." (PMID 42137503, 2026). "We showed that BA inhibits the growth of tumour cells by inducing the SEMA3A/PLXNA1/NRP1 pathway and prevents cell growth by inducing oxidative damage and activating apoptosis through excessive ROS generation." (PMID 40318008, 2025). "Since Sema6D derived from nonhematopoietic cells seemed to regulate CD8+ T cell function in the TME, we investigated the role of Plexin-A1 and Plexin-A4, which are receptors for Sema6D, in T cells isolated from tumor-draining LNs." (PMID 38329122, 2024). "Inhibition of plexin-A1 decreased cell proliferation in these tumor cells and suppressed their glycolytic activity." (PMID 37627074, 2023). "At the endpoint of 7 weeks, mean tumor diameter of NT-BTSCs (13.1 mm ± 2.4) was greater than that of Nrp1-KD BTSCs (0.0 mm ± 0.0), and approached significance for PlxnA1-KD BTSCs (5.6 mm ± 1.4)." (PMID 33302912, 2020). "Both Nrp1-KD and PlxnA1-KD demonstrated a slower rate of growth than NT-BTSCs, as determined by changes in tumor diameter, though only Nrp1-KD reached statistical significance." (PMID 33302912, 2020). "It has been successfully used in vitro to antagonize Plexin‐A1 signalling and cell migration, while it showed anti‐tumour effect in vivo." (PMID 31566924, 2019). "Subsequently, we found that knockdown of plexin-A1 expression in tumor cells effect the HUVECs tube formation, migration and tumor growth in vivo, which give us a valid support that plexin-A1/VEGFR2 signaling pathway is value in tumor angiogenesis." (PMID 29262812, 2017). "It is interesting to note that the expression of both VEGFR3 and PLXNA1 in PBMCs was upregulated in smaller tumor sizes (<2 cm) and stage 1 disease in addition to being overexpressed in TNBC." (PMID 28607365, 2017). "In recent years, plexin-A1 was found to play critical roles in tumor biology such as cell survival and anchorage-independent growth, as well as angiogenesis." (PMID 29262812, 2017). "Furthermore, PLXNA1 is involved in regulating critical processes such as the tumor microenvironment, angiogenesis, and epithelial–mesenchymal transition through various molecular pathways, thereby promoting tumor growth, migration, and metastasis." (PMID 41040533, 2025). "For instance, the co-expression of lnc-ASAP1-IT1 with PLXNA1, a protein involved in membrane signaling, suggested the existence of potential regulatory interactions that contribute to metabolic shifts within the tumor microenvironment." (PMID 40248203, 2025). "Additionally, although sema3A usually functions as a tumor suppressor, it was discovered that plexin-A1 can mediate sema3A oncogenic signals in lung cancer cells." (PMID 37627074, 2023). "Another study suggested that NRP1, in combination with Plexin-A1, was correlated with poor prognosis in glioblastomas and may contribute to tumor growth." (PMID 34277411, 2021). "PLXNA1 and PLXNA3 were also reported to promote tumor growth and associate with poor prognosis." (PMID 32640719, 2020). "In summary, based on our systematic analyses of NRPs and PLXNs in terms of their expression, association with patient survival, immune subtype, and tumor infiltration, we found that NRP1, NRP2, PLXNA1, PLXNA3, PLXNB3, PLXNC1, PLXND1 were mainly associated with poor prognosis." (PMID 32640719, 2020).
tumor (continued). "Additionally, PLXNA1 expression in PBMCs was significantly downregulated in cases with T4 tumor size compared to T1 (p = 0.030) and T2 (p = 0.049)." (PMID 28607365, 2017). "To examine whether plexin-A1 konckdown affects tumor formation in vivo, we subcutaneously inoculated shNC MGC803 cells, shPlexin-A1 MGC803 cells or RPMI-1640 medium (blank control group) into BALB/c nude mice." (PMID 29262812, 2017). "It is demonstrating that VEGF promote tumor angiogenesis via plexin-A1 /VEGFR2 signaling." (PMID 29262812, 2017). "LIMK1, HOXC6 and PLXNA1 represent potential novel candidate genes for driving tumor growth of ERMS." (PMID 24009521, 2013). "One of these ligands, SEMA3F exhibits well-documented tumor-suppressive activities mediated through NRP2 and plexinA1 (PLXNA1)." (PMID 41391772, 2025). "Here we demonstrate that Neuropilin-1 (NRP1) and Plexin-A1 and Plexin-A4 are upregulated on stimulated CD8+ T cells, allowing tumour-derived SEMA3A to inhibit T cell migration and assembly of the immunological synapse." (PMID 38609390, 2024). "Here the authors investigate how these interactions affect CD8+ T cells in tumour immunity, showing that NRP-1, Plexin-A1 and Plexin-A4 are upregulated on T cells allowing tumour derived SEMA3A to inhibit CD8+ T cell migration and function." (PMID 38609390, 2024). "A peptide, specifically targeting Plexin-A1, has shown promising results in reducing proliferation and angiogenesis as well as blocking tumor cell spread following disruption of NRP1 and Plexin-A1 heterodimerization." (PMID 34277411, 2021). "Immunostaining and PCR analysis revealed that BTSCs highly express Sema3A and its receptors Nrp1 and PlxnA1, with expression of Nrp1 in the CD133 positive BTSCs, and absence in differentiated tumor cells." (PMID 33302912, 2020). "Together with plexins (plexin-A1) and neuropilins (Nrp-1 and Nrp-2), semaphorins (including SEMA3A) have the ability to interrupt vascular formation and tumor vascularization." (PMID 30971898, 2019). "The role of Plexin A1 needs to be specifically studied in TNBC and in conjunction with VEGFR3 to determine if in this type of aggressive cancer the tumor suppressive activity of Plexin A1 is lost." (PMID 28607365, 2017). "PLXNA1 also had additional roles in arresting ERMS cells in early stages of muscle differentiation, in enhancing tumor cell migration, and in altering anchorage-independent growth." (PMID 24009521, 2013). "In total, our data uncovered important roles for CCND2, HOXC6 and PLXNA1 in regulating ERMS proliferation, validating the role of several novel genes in regulating continued tumor cell proliferation in human ERMS cells." (PMID 24009521, 2013). "Of note, endogenous CD4+CD25+FoxP3+ T cells found within the tumor expressed both NRP1 and Plexin-A1 as well as TGFβR1-2, indicating that this subset of T cells might be modulated differently from CD8+ T cells." (PMID 38609390, 2024). "While plexin-A1 clearly conveys sema3A-induced anti-angiogenic signals, the effects of plexin-A1 transduced sema3A signals on tumor cells are not as clear." (PMID 37627074, 2023). "Similarly, the knockdown of Plexin-A1 in the zebrafish GBM model revealed its role in inducing both developmental and GBM tumour-specific pro-angiogenesis, identifying Plexin-A1 as a potential therapeutic target for treating GBM by blocking the pro-angiogenic effects." (PMID 36077320, 2022). "In contrast, PLXNA1 showed higher expression in C1, C2 and C6, NRP2 and PLXNC1 had increased expression in C6, indicating that these genes may mainly play a tumor promoter role as patients characterized into those subtypes had worse survival due to higher proliferation rate and enrichment of TGFβ." (PMID 32640719, 2020). "In addition, plexin-A1 and VEGFR2 signals appeared to localize simultaneously in the tumor-associated vascular endothelial cells and tumor cells, but not in the normal gastric tissues." (PMID 29262812, 2017).
tumor (continued). "Moreover, we report differential PBMC expression profiles that correlate inversely with disease stage (SEMA4A, SNAI1, PLXNA1 and VEGFR3) and can differentiate between the TNBC and non-TNBC tumor subtypes (VEGFR3 and PLXNA1)." (PMID 28607365, 2017).
cancer (12 papers, 2017 to 2025). A tumor composed of atypical neoplastic, often pleomorphic cells that invade other tissues. "A recent study found that PLXNA1 was upregulated in many cancer types, and its increased expression was associated with poor prognostics and correlated with more aggressive subtypes of immune infiltrates." (PMID 35053566, 2022). "For example, PLXNA1 was upregulated in majority of the tested cancer tumors, and the increased expression was mainly associated with increased disadvantage for both OS and PFI." (PMID 32640719, 2020). "Each gene in the risk evaluator, PLXNA1, MARCKSL1, IQGAP3, PFN2, PON1, and TAK, has been reported to be associated with the prognosis or progression of cancer." (PMID 37954858, 2023). "The genes PLXNA1, PLXNA2 and PLXNA4 are enriched in cellular development - axon guidance processes and 68 pan-cancer mutations show a significant clustering of mutations, near a predicted functional site (i.e. based on the most highly conserved positions within the FunFam) and an IBIS PPI site." (PMID 30670742, 2019). "We observed that levels of these genes showed great heterogeneity in different cell lines as in patient tumors, with PLXNA1 having the highest expression and PLXNA4 having the lowest expression across all cancer cell lines." (PMID 32640719, 2020). "The other major cluster is further separated into several subclusters, with one subcluster including PLXNA1, PLXNA3, and SEMA3F showing predominantly increased expression in cancer tumors." (PMID 32640719, 2020). "We highlight cancer-specific down regulation of NRP-1, SNAI1 and SEMA4A in PBMCs with a further decrease of SNAI1, SEMA4A, VEGFR3 and PLXNA1 in patients with advanced disease." (PMID 28607365, 2017). "Besides, the roles of seven genes (NR1D2, TANK, LRSAM1, PLXNA1, INHBE, HDGF, and ARAF) in SCLC have not been reported, however those genes have been reported to play a vital role in other type cancer." (PMID 34741430, 2021).
genetic disease (2 papers, 2023 to 2024). "Nine plexin genes have been identified in humans, but despite the apparent importance of plexins in development, only biallelic PLXND1 and PLXNA1 variants have so far been associated with Mendelian genetic disease." (PMID 38458752, 2024).
PLXNA1 also shares sentences with these, for which no sentence is quoted: Intellectual disability (2 papers); brain malformations (1); cervical cancer (1); colorectal cancer (1); cranial neuropathies (1); diabetes (1); Facial palsy (1); gastric tumors (1); hematoma (1); hypogonadotropic hypogonadism (1); infection (1); lentivirus infection (1); liver cancer (1); lung carcinoma (1); malignant pleural mesothelioma (1); metastatic tumors (1); neurodevelopmental disorder (1); osteosarcoma (1); pancreatic ductal adenocarcinoma (1); peripheral axonal neuropathy (1); psychiatric diseases (1); schizophrenia (1); Stroke (1); type 2 diabetes (1); ulcerative colitis (1); uveal melanoma (1).